SLC10A7 (solute carrier family 10 member 7)
Description:
Involved in teeth and skeletal development. Has an essential role in the biosynthesis and trafficking of glycosaminoglycans and glycoproteins, to produce a proper functioning extracellular matrix. Required for extracellular matrix mineralization. Also involved in the regulation of cellular calcium homeostasis. Does not show transport activity towards bile acids or steroid sulfates (including taurocholate, cholate, chenodeoxycholate, estrone-3-sulfate, dehydroepiandrosterone sulfate (DHEAS) and pregnenolone sulfate).
Synonyms: C4orf13; P7; MGC25043; DKFZp566M114; DKFZp313H0531; DKFZp779O2438; SSASKS
Tractability: Antibody: UniProt places it where antibodies can reach, with high confidence; its Gene Ontology location is reachable by antibodies, with high confidence; UniProt predicts a signal peptide or a membrane-spanning region.
Gene: Protein-coding gene on chromosome 4 (146,253,975 to 146,522,372, reverse strand). Ensembl gene ENSG00000120519.
Subcellular location: Cell membrane; Endoplasmic reticulum membrane; Golgi apparatus membrane
Gene Ontology:
Molecular function: protein binding
Biological process: bone development; heparin proteoglycan biosynthetic process; intracellular calcium ion homeostasis
Cellular component: endoplasmic reticulum; endoplasmic reticulum membrane; Golgi apparatus; Golgi membrane; plasma membrane
Genetic constraint (gnomAD): Loss-of-function variants: 21 observed, 31.32 expected, observed/expected ratio (o/e) 0.67, 90% interval 0.47 to 0.97. The upper end of that interval is the gene's LOEUF score, 0.97, which puts it in group 4 of 6, group 1 being the genes least tolerant of losing a copy. Missense variants: 240 observed, 346.51 expected, observed/expected ratio (o/e) 0.69, 90% interval 0.62 to 0.77. Synonymous variants: 124 observed, 125.82 expected, observed/expected ratio (o/e) 0.99, 90% interval 0.85 to 1.14.
Gene-disease validity (ClinGen):
ClinGen rates the evidence that SLC10A7 causes each of these diseases.
short stature, amelogenesis imperfecta, and skeletal dysplasia with scoliosis (autosomal recessive): Definitive.
Homologues: Orthologues: chimpanzee SLC10A7 (98% identical), macaque SLC10A7 (98% identical), dog SLC10A7 (97% identical), guinea pig SLC10A7 (96% identical), mouse Slc10a7 (95% identical), rat Slc10a7 (94% identical), pig SLC10A7 (94% identical), tropical clawed frog slc10a7 (83% identical), rabbit SLC10A7 (77% identical), zebrafish slc10a7 (75% identical).
Diseases named in the same sentence as SLC10A7 in open-access papers:
SLC10A7 is named in the same sentence as 10 diseases in open-access papers, as found by Europe PMC text mining. Sharing a sentence is not in itself a finding about the gene and the disease. The quoted sentences say what the papers report.
amelogenesis imperfecta (7 papers, 2018 to 2023). Amelogenesis imperfecta (AI) represents a group of developmental conditions affecting the structure and clinical appearance of the enamel of all or nearly all the teeth in a more or less equal manner, and which may be associated with morphologic or biochemical changes elsewhere in the body. "SLC10A7 mutations are associated with skeletal dysplasia, amelogenesis imperfecta, and decreased bone mineral density." (PMID 36726969, 2022). "In conclusion, the occurrence of variants in the SLC10A7 gene should be considered in patients with skeletal dysplasia and amelogenesis imperfecta." (PMID 34671644, 2021). "Genetic variants in the human SLC10A7 gene are associated with skeletal dysplasia and amelogenesis imperfecta and reveal loss of function on cellular calcium influx." (PMID 34671644, 2021). "Very recently, several mutations within the human SLC10A7 gene were identified in patients with skeletal dysplasia, amelogenesis imperfecta and decreased bone mineral density." (PMID 32350310, 2020). "Recently, mutations in the human SLC10A7 gene were associated with skeletal dysplasia, amelogenesis imperfecta, and decreased bone mineral density." (PMID 32350310, 2020). "This study presents evidence that homozygous mutations in SLC10A7 are responsible for skeletal dysplasia and amelogenesis imperfecta." (PMID 30082715, 2018). "Using exome sequencing, we identify homozygous mutations in SLC10A7 in six individuals with skeletal dysplasia with multiple dislocations and amelogenesis imperfecta." (PMID 30082715, 2018). "Thus, amelogenesis imperfecta can be considered as a new clinical feature indicative of SLC10A7 mutations." (PMID 30082715, 2018). "Even if few features are typical for some disorders, characteristic hand anomalies in CANT1, IMPAD1, CHSY1, and TGDS-related conditions or amelogenesis imperfecta in dysplasia due to mutations in SLC10A7, for example, may help clinicians to orientate the clinical diagnosis." (PMID 34220933, 2021). "Short Stature, Amelogenesis imperfecta, and Skeletal dysplasia with Scoliosis (SSASKS, OMIM #618,363) was first related to mutations in the solute carrier family 10 member 7 (SLC10A7) gene (OMIM #611,459) in 2018." (PMID 38037133, 2023). "In addition to the already established disease-related SLC10A7 variants, the occurrence of L210F might be considered in patients with skeletal dysplasia or amelogenesis imperfecta." (PMID 34671644, 2021). "Amelogenesis imperfecta seems to be a phenotypic feature specific to SLC10A7 deficiency within the group of chondrodysplasias with multiple dislocations, suggesting that amelogenesis imperfecta is not due to a defect in proteoglycan synthesis but to a different function of SLC10A7." (PMID 30082715, 2018).
glioma (1 paper, 2023). A benign or malignant brain and spinal cord tumor that arises from glial cells (astrocytes, oligodendrocytes, ependymal cells). "For instance, circHECTD1 contributes to glioma progression by regulating the miR-296-3p/SLC10A7 axis, and circ-TOP2A regulates glioma progression via miR-346/SUSD2." (PMID 37575469, 2023).
tobacco use disorder (1 paper, 2026). "The other five loci contained promising coding and expression variants, including Trak2, a gene previously associated with CUD in human GWAS and Slc10a7, Plcl1, and Satb2 which have been associated with alcohol and tobacco use disorder." (PMID 42277005, 2026).
skeletal dysplasia (9 papers, 2018 to 2023). Any Mendelian diseases that affects growth and development of the skeleton. "The key phenotype to distinguish individuals with mutation in SLC10A7, within the wide spectrum of skeletal dysplasia, was the hypomineralized/hypomature enamel defects observed in all the individuals and the hypoplastic lower jaw." (PMID 37228816, 2023). "Importantly, skeletal phenotypes were described for Fam20c (non-lethal Raine syndrome), Lrrk1 (osteosclerotic metaphyseal dysplasia), Pappa2 (short stature), Sfrp4 (Pyle's disease), and Slc10a7 (skeletal dysplasia) prior to knowledge of the human skeletal dysplasias when mutated in humans." (PMID 32117046, 2019). "However, AI is the key feature indicative of SLC10A7 mutations in patients with skeletal dysplasia." (PMID 31191616, 2019).
cancer (2 papers, 2022 to 2024). A tumor composed of atypical neoplastic, often pleomorphic cells that invade other tissues. "Proteins linked to cancers (e.g., the tumour suppressor, CDKN2A), CNS disorders (e.g., the myelin constituent, PMP22), and developmental disorders (e.g., skeleton and tooth development protein, SLC10A7) were represented at fCEAA and fEAA extremes." (PMID 39401228, 2024). "Multiple studies have demonstrated that SLC10A7 plays an important role in various human cancers." (PMID 36726969, 2022).
tumor (2 papers, 2022 to 2024). "Thus, as one of the most important TPRs, SLC10A7 is not only crucial for the maintenance of the tumor microenvironment of LGG but is also essential for the proliferation and migration of LGG." (PMID 36726969, 2022).
SLC10A7 also shares sentences with these, for which no sentence is quoted: chondrodysplasia (1 paper); Obesity (1); scoliosis (1); short stature, amelogenesis imperfecta, and skeletal dysplasia with scoliosis (1).